RNVU1-3 (RNA, variant U1 small nuclear 3)
Synonyms: vU1.3; RNU1-113; vU1.12; RNU1-151; RNVU1-12
Gene: Small nuclear RNA gene on chromosome 1 (148,402,715 to 148,402,875, forward strand). Ensembl gene ENSG00000201183.
Gene Ontology:
Molecular function: pre-mRNA 5'-splice site binding
Biological process: mRNA 5'-splice site recognition
Cellular component: U1 snRNP
Homologues: Orthologues: dog U1 (75% identical), rabbit U1 (64% identical). Paralogues in human: RNVU1-4 (93% identical), RNVU1-30 (93% identical), RNU1-1 (84% identical), RNU1-2 (84% identical), RNU1-27P (84% identical), RNU1-28P (84% identical), RNU1-3 (84% identical), RNU1-4 (84% identical), RNVU1-18 (84% identical), RNVU1-29 (84% identical), RNVU1-7 (84% identical), U1 (84% identical), and 134 more.